SUZ12 (SUZ12 polycomb repressive complex 2 subunit)
Diseases named in the same sentence as SUZ12 in open-access papers (continued):
Sharing a sentence is not in itself a finding about the gene and the disease.
tumor (continued). "Similar to that of Usp22-targeted deletion, treatment of tumor cells with USP22i-S02 led to a substantial reduction in EZH2, but not EED, EZH1, and SUZ12." (PMID 41252204, 2025). "In contrast, SUZ12 did not co-localize with EZH2 or EED, suggesting a possible disruption of PRC2 complex formation or altered subcellular dynamics in the tumor context." (PMID 40766612, 2025). "High pPAK1 was observed in NF1-mutant, SUZ12-mutant ST88-14 MPNST cells independent of CRISPRi suppression of NF2, suggesting PAK1 activation may be conserved across de-differentiated Schwann cell tumors after loss of either tumor suppressors or epigenetic regulators." (PMID 38216572, 2024). "Interestingly, USP22 appears to selectively control EZH2 but not any other PCR2 complex proteins including EZH1, SUZ12, and EED in tumor cells." (PMID 41252204, 2025).
cancer (117 papers, 2008 to 2025). A tumor composed of atypical neoplastic, often pleomorphic cells that invade other tissues. "In NSCLC, compared with neighboring normal tissues, SUZ12 mRNA expression was higher in 40 cancer tissues and associated with worse clinicopathological features." (PMID 39400513, 2024). "We also observed a similar mutational signature at SUZ12/EZH2-binding sites in several other cancer types." (PMID 32047165, 2020). "Accumulating evidence has demonstrated that SUZ12 overexpression significantly associated with aggressiveness in multiple human cancers." (PMID 28228691, 2017). "Taken together, we propose that SUZ12 is a novel cancer biomarker of TSCC which significantly associates with cervical node metastasis." (PMID 28228691, 2017). "It remains an interesting question to determine the expression level of SUZ12 in the metastatic lesions and its clinical significance, and further unravel its associated mechanistic underpins during cancer metastatic spread." (PMID 28228691, 2017). "Polycomb site methylation has now been accepted as a hallmark of cancers, and so the enrichment of polycomb proteins, SUZ12 and EZH2, should be an innate quality." (PMID 26464434, 2016). "The mutations of SUZ12 often are found in some cancer, for example, SUZ12 mutations cause the malignant transformation of peripheral nerve sheath tumors." (PMID 26349457, 2016). "Suz12 belongs to the Polycomb Repressive Complex 2 and its up-regulation has been associated with cancer and stem cell compartment maintenance." (PMID 22920668, 2012). "EZH2 and SUZ12 variants have been reported in other cancers and can be viewed through OncoKB." (PMID 40766612, 2025). "In addition, SUZ12 regulates chromatin modification and the mutation can contribute to proliferation of cancer cell and T cells." (PMID 37142644, 2023). "In addition, EZH2 loss significantly promoted the development of myelodysplastic syndrome induced by transcription factor Runx1 mutation, and loss of SUZ12 synergizes with neurofibromin 1 (NF1) mutations to amplify Ras signaling to drive cancer." (PMID 36076977, 2022). "This might explain why, in contrast to nf1, single allele loss of suz12 in zebrafish is sufficient to promote the initiation of malignant tumors in a sensitized background." (PMID 32651197, 2020). "To further understand how DEGs were regulated, we analysed transcription factor (TF) binding using Enrichr and observed that DEGs were enriched for targets of TFs associated with self-renewal and cancer stem cell function (SUZ12, SOX2, REST, EZH2, SMAD4 and NANOG)." (PMID 31014368, 2019). "Previous studies have provided clues to support the notion that SUZ12 is usually overexpressed in several human cancers and might serve as a putative pro-oncogene associated with tumorigenesis." (PMID 28228691, 2017). "SUZ12 was reported to be overexpressed in tissues of some cancer types and its upregulation is correlated with worse clinicopathological features or a poor prognosis." (PMID 39400513, 2024). "Specifically, miR-200 levels decrease during cancer stem-cell formation, which leads to an increase in SUZ12 expression and H3-K27me3 of the E-cadherin gene, repressing their activity." (PMID 37345170, 2023). "By conducting a structure–activity relationship study that focused on exploring various linkers, we identified MS147, which preferentially degraded PRC1 components, BMI1 and RING1B, over PRC2 components: EED, EZH2, and SUZ12, in multiple cancer cell lines." (PMID 36737841, 2023). "Other miRNAs such as mir-767-5p, miR-105, and miR-200 target SUZ12 to regulate glioma cell proliferation and the formation and maintenance of cancer stem cells." (PMID 37345170, 2023).
cancer (continued). "SUZ12 is a member of the polycomb repressive complex 2 (PRC2) which induces gene repression-related H3K27me3 at target gene promoter in many cancers." (PMID 35864549, 2022). "According to previous studies, genetic alterations including loss of NF1, EED, and SUZ12, have been demonstrated to activate the RAS/MAPK pathway in various human cancers including MPNSTs." (PMID 35875109, 2022). "The present model also reconciles some published data on cancer, which indicate that, in several human cancer cells, Kaiso is found in the cytoplasm and Suz12 or EZH2 is overexpressed in the nucleus." (PMID 30940992, 2019). "We found that USP3 and SUZ12 were expressed at high levels in the nucleus and cytoplasm of cancer cells from two patients." (PMID 31234902, 2019). "Recently, it has been shown that upregulation of SUZ12 promotes metastasis through the regulation of EMT in cancer cells." (PMID 31234902, 2019). "As expected, hypermethylated CpGs in aging and cancer were associated in all tissues with the presence of EZH2 and SUZ12, components of the polycomb complex which directly deposits the H3K27me3 mark." (PMID 29504244, 2018). "For example, gain-of-function mutations in EZH2, EED or SUZ12 occur in multiple cancer types, and both EZH2 and EED are current targets for cancer therapy." (PMID 30005706, 2018). "With regard to the potential effectors of the distinct chromatin signatures, enrichment analyses of transcription factors revealed the presence of EZH2 and SUZ12 polycomb components at DNA hypermethylated sites, both in cancer and aging." (PMID 29504244, 2018). "High SUZ12 expression was mainly identified in the nucleus and much less in the cytoplasm in cancer cells, whereas weak staining was observed in normal tongue epithelial cells." (PMID 28228691, 2017). "SUZ12 is involved in cellular differentiation and has been found involved in the progression of a number of cancers." (PMID 28949986, 2017). "In particular, pharmacologic or genetic disruption of SUZ12 inhibited cell proliferation and invasion, and disrupted the maintenance of cancer stem cell both in vitro and in vivo." (PMID 28228691, 2017). "SUZ12 is overexpressed in many human cancers, as ovarian cancer, mantle cell lymphoma or non-small cell lung cancer and breast cancer." (PMID 27471434, 2016). "Recent studies implied that PRC2 and its subunits (SUZ12 and EZHZ) were often deregulated in various cancer types and their overexpressions were closely associated with carcinogenesis." (PMID 25265536, 2014). "EZH2 and SUZ12, components of the polycomb PRC2 complex, have been implicated in several types of cancer." (PMID 21712824, 2011). "SUZ12 expression is regulated by the pRB/E2F pathway and is required for cellular proliferation of normal and cancer cell lines." (PMID 18628979, 2008). "Consistent with the role of PcG proteins in cancer formation, the SUZ12 gene locus is translocated in human Endometrial Stromal Sarcomas (ESS) with high frequency leading to the expression of an uncharacterized fusion protein." (PMID 18628979, 2008). "It is interesting to note that the part of SUZ12 that is involved in this translocation exclude K75 suggesting that the physiological functions of SUZ12 sumoylation will be lost in cancers harboring this translocation." (PMID 18628979, 2008). "Of these, key cancer-associated genes shown to be upregulated by the SySa fusion were downregulated by TAK-981 treatment, including CDX2, HOXA10, SUZ12, TYMS, AURKB, and HOXC10 and SMC2." (PMID 40804185, 2025). "At present, regarding the roles of molecular mechanism of SUZ12 in promoting cancer, previous studies displayed that it may silence p2111 and p2712 and upregulate cyclin D16 and MMP2/921 expression." (PMID 39400513, 2024).
cancer (continued). "Moreover, subunits of PCR2, such as SUZ12, are inhibited by the miR-200 family in cancer stem cells." (PMID 35815953, 2022). "Interestingly, the miR-200 family (miR200b/miR200c) directly inhibits the SUZ12 subunit of the PCR2 in cancer stem cell lines." (PMID 35815953, 2022). "Finally, we generated a Python application to analyze the correlation of EZH2/SUZ12/EED gene knockouts by CRISPR with the alterations detected in the cancer cell lines using DepMap data." (PMID 34202528, 2021). "Reference-based analysis of these target genes based on their potential roles in regulating DNA damaging responses and cancer progression led us to select SUZ-12 (polycomb repressive complex 2) and MDC-1 (mediator of DNA-damage checkpoint 1) as key target genes of miR-489." (PMID 32784600, 2020). "This affected 17/333 pathway-associated genes including six known cancer genes (HNRNPA2B1, STAG2, TCF7L2, SUZ12, CLTC, and ZNF521), Thus, the integration procedure prioritized specific pathway-related genes compared to their original rankings in individual mutation datasets." (PMID 32024846, 2020). "SUZ12 is upregulated in many human cancers including colon, liver, gastric and breast cancers." (PMID 31234902, 2019). "Noticeably, Our findings and others point to an interesting link and positive association between SUZ12 expression and cancer metastasis irrespective of cancer origin and primary site." (PMID 28228691, 2017). "Furthermore, NORED exclusive-associated genes were uniquely enriched in genes characterized by H3K27me3 with polycomb proteins (SUZ12 or EED) bound to promoters that experience de novo DNA methylation in cancers (18 genes, q=6.94×10−9)." (PMID 29387450, 2017). "All but SUZ12 in the CESC cohort are similarly elevated as compared to HPV- cancers." (PMID 29069809, 2017). "Therefore, it remains an open and interesting question to unravel the roles of SUZ12 and its regulatory network during tongue tumorigenesis and to develop efficient approaches to therapeutically targeting SUZ12 in cancer." (PMID 28228691, 2017). "Previous studies have suggested that the SUZ12, one of the core components of PRC2, might be an oncogene driving tumorigenesis and serve as a novel diagnostic biomarker and therapeutic target for cancer treatment." (PMID 28228691, 2017). "While SUZ12 and EED mutations have only been found to have loss-of-function effects, EZH2 mutations have been found to have both activating and inactivating functions in different cancers." (PMID 27471434, 2016). "SUZ12-depletion induced some CCRI genes in non-cancer lines." (PMID 26030458, 2015). "In addition, by integrating the chromatin profiles from ENCODE, the authors also found an enrichment of the PRC2 subunits EZH2 and SUZ12 in the promoters that are gained/lost in cancer, highlighting the role of PRC2 in maintaining the cancer chromatin landscape." (PMID 36653445, 2023). "Consistent with a previous report, we found that around 35% of the sequences frequently hypermethylated in cancer and unmethylated in at least one of the NTTs analyzed contained chromatin-repressive marks at their promoters (228-277/697 harbored meK27, and 236/697 contained SUZ12)." (PMID 18820729, 2008). "Further analysis of cancer-related genes showed that TPA and mezerein exposure upregulates several oncogenes, including Hmga1, Foxm1, Igf2bp2, Anln, Ezh2, and Suz12." (PMID 40182023, 2025). "These 1,670 genes involved well-established cancer-related genes, including MYC, MYB, BRCA2, ERCC4, and MET for s1 subtype and TERT, BCL2, and SUZ12 for s3 subtype." (PMID 36731467, 2023).
cancer (continued). "ChIP-seq Enrichment Analysis (ChEA) for these up-regulated genes in the KO cells demonstrated over-representation of transcription factors of SUZ12, AR, Nrf2, SMAD4, as well as SOX2 and Nanog important for the stem cells and cancer stem cells." (PMID 37151890, 2023). "The SUZ12, REST, and EZH2 genes were reported to contribute to the stemness of cancer cells, and they exhibited higher expression levels in the higher NAS group." (PMID 36309750, 2022). "EZH2 combines with EED, SUZ12, and RBBP4 to generate a PRC2 subunit, which is overexpressed in multiple types of cancer." (PMID 36686830, 2022). "The impact of EGCG on histone methylation has so far been analyzed from the level of cancer cells and polycomb group (PcG) protein, particularly EZH2, but also Suz12, Mel18 and Bmi-1." (PMID 32429384, 2020). "In our model, we have assessed suz12 LOF-mediated carcinogenesis in a dose-dependent manner and translated our results based on current studies of human cancer genetics." (PMID 32651197, 2020). "Five TFs, SUZ12, SMAD4, REST, EZH2 and NFE2L2, were found to be enriched in all four cancers, suggesting that transcriptional dysregulation of tumors with aberrant AMPK signaling involved direct physical associations of these TFs with target DEGs." (PMID 32807122, 2020). "Our analyses focused on several key NMPs including SATB1/2, SAFB1/2, EZH2, SUZ12, BMI1, PCL3, RAE28, and CTCF, as these NMPs have been shown to be aberrantly expressed in cancers." (PMID 33124191, 2020). "Consistent with dysregulation of PRC2 in several human cancers, a robust expression of EZH2, SUZ12, and EED proteins was seen on the western blots for all MCL cell lines analyzed." (PMID 32850364, 2020). "Complementary to this notion, previous studies have demonstrated that the metastasis-regulator Snail recruits SUZ12 to the CDH1 promoter and represses E-cadherin expression, thus in turn triggers EMT and cancer metastasis." (PMID 28228691, 2017). "The expression of EZH2, EED, and SUZ12 is controlled by the pRB/E2F pathway and PRC2 activity is essential for the proliferation of primary and cancer cell lines." (PMID 18628979, 2008). "This study found that SUZ12 expression is upregulated in both CHD and T2D, revealing that SUZ12 may be involved in non-cancer diseases." (PMID 41306918, 2025). "ALK expression was associated with methylation of regions/probes harboring repressive histone marks as indicated by the enrichment of chromatin regulators of the PRC2 complex (EZH2, SUZ12, and JARID2), which has been described as “epigenetic switching” in cancer." (PMID 38585847, 2024). "We also sequenced the polycomb complex repressor 2 (PRC2) components EZH2, SUZ12, and EED, as frequently co-altered with RAS pathway genes in other cancers in 104 samples from our cohort, and found that 50% and 13.8% of RAS+ and RAS− cases, respectively had concomitant PRC2 alteration (p < 0.0001)." (PMID 35354920, 2022). "Interestingly, we found decreased levels of both Suz12 and EZH2 subunits in CD4+ T cells co-cultured with MDA-MB-231 cancer cells." (PMID 34439305, 2021). "In this study, ChIP-seq was performed on an LCL for BMI1 and SUZ12, subunits of PRC1 and PRC2, respectively—two protein complexes shown to be critically important in the regulation of genes involved in differentiation, proliferation and cancer development." (PMID 30649516, 2019). "USP3 and SUZ12 were only expressed in cancer cells, whereas E-cadherin was predominantly expressed in normal epithelial cells." (PMID 31234902, 2019). "Suz12 is a key component of the polycomb repressive complex 2 (PRC2), which has been confirmed to promote invasion and metastasis by epigenetically silencing metastasis suppressors in many malignant tumors." (PMID 27582550, 2016).
cancer (continued). "Interestingly, existing evidence also revealed that the dysfunction of the PRC2 complex comprising of subunits such as EZH2, SUZ12, and EED could expedite abnormal hypermethylation of H3K27 which induces carcinogenesis in a wide array of cancers." (PMID 33882457, 2021). "Moreover, both HMGA1 and SUZ12/CCDC43 were highly expressed in cancer cells but not in normal gastric tissues, and their expressions were positively correlated." (PMID 34167089, 2021). "Further, this analysis also strongly suggested that SNAI2, SUZ12 and HDAC1 might form a repressor complex, implicating the interaction of transcriptional factors and histone modification regulators to have a pivotal role in miR-204-5p-mediated inhibition of cancer progression." (PMID 31938073, 2020). "Although the epigenetic role of PRC2 is reported to be inhibited by the upregulated H3K4me3, the core components, EZH2 and SUZ12, have been shown to have oncogenic roles independent of PRC2 in several cancer types including NSCLC." (PMID 33916417, 2021). "Westerns revealed that SUZ12, EZH2 and/or H3K27me3 levels were typically elevated in cancer lines compared to non-cancer lines." (PMID 26030458, 2015). "Moreover, the core components, EZH2 and SUZ12, have been reported to have oncogenic roles independent of PRC2 in several cancer types including NSCLC." (PMID 33916417, 2021). "We showed that SNAI2 could recruit EZH2 but not SUZ12, suggesting SNAI1 and SNAI2 have different functions and non-overlapping roles in cancer cells and might cooperate to recruit PRC2 to the CDH1 promoter." (PMID 31938073, 2020).
infection (5 papers, 2012 to 2025). The state of being infected such as from the introduction of a foreign agent such as serum, vaccine, antigenic substance or organism. "Other epigenetic modulators like DNA demethylases TET2 and TET3, histone variant genes, INO80 complex, PRC2 complex genes, EED and SUZ12 were also associated with DNA methylation changes upon infection." (PMID 27112593, 2016). "The relative mRNA levels of Ezh2 and Suz12 showed different expression levels in the infection group." (PMID 38992966, 2025). "The loss of c-Src protein was complete at 96 h post-infection, correlating with an increased AMP:ATP ratio, AMPK activation, mTORC1 suppression, and reduced Ezh2 and Suz12 protein expression." (PMID 31263101, 2019). "To determine whether the observed, infection-dependent, increase in PcG immunofluorescence could be explained by an overall increase in protein expression, we next performed western blot analysis for the PRC2 proteins EZH2 and SUZ12 as well as the PRC1 proteins BMI1 and RING1B." (PMID 22279536, 2012).
hematologic malignancies (3 papers, 2020 to 2024). "In contrast, loss-of-function mutations in PRC genes, such as EZH2, EED, SUZ12, BCOR, and BCORL1, have been found in various hematological malignancies, suggesting their tumor suppressor functions." (PMID 33374737, 2020). "Notably, actionable or druggable gene mutations in EZH2, SUZ12, or EED are mostly observed in hematologic malignancies." (PMID 39565059, 2024).
CNS tumor (2 papers, 2019 to 2021). "Transfection of miR‐367 inhibitor increased SUZ12 expression in all types of CNS tumor cells, with or without OCT4A overexpression." (PMID 31402560, 2019).
blood cancer (1 paper, 2020). "Loss of SUZ12 promotes the onset of a variety of malignancies, including blood cancer subtypes." (PMID 32651197, 2020).